FOXCUT (FOXC1 upstream transcript)
Synonyms: TCONS_00011636; formerly LINC01379
Gene: Long non-coding RNA gene on chromosome 6 (1,593,368 to 1,607,358, forward strand). Ensembl gene ENSG00000280916.
Diseases named in the same sentence as FOXCUT in open-access papers:
FOXCUT is named in the same sentence as 12 diseases in open-access papers, as found by Europe PMC text mining. Sharing a sentence is not in itself a finding about the gene and the disease. The quoted sentences say what the papers report.
breast carcinoma (4 papers, 2014 to 2021). "Recent studies have demonstrated that high expression levels of FOXCUT and FOXC1 are strongly associated with poor prognosis in patients with base-like breast cancer (BLBC)." (PMID 27686732, 2016). "Conversely, inhibition of FOXCUT impaired the invasion and migration capabilities of the breast cancer cell lines MDA-MB-231 and MDA-MB-468." (PMID 27686732, 2016). "To further confirm these results, we also investigated the expression of FOXC1 and FOXCUT in four hepatocellular cancer cell lines and five breast cancer cell lines, and found that both FOXC1 and FOXCUT expressions were higher in these cancer cells than in normal cells." (PMID 24889262, 2014). "FOXCUT expression was found enhanced in Basal-Like Breast Cancers (BLBCs) but not in other non-basal like breast cancer subtypes, suggesting that FOXCUT may function as specific biomarker in BLBCs." (PMID 32183847, 2020).
hepatocellular carcinoma (2 papers, 2014 to 2023). A malignant tumor that arises from hepatocytes. "The lncRNA molecules NBAT-1 and FOXCUT have been found to have increased serum levels in patients with hepatitis C virus-induced hepatocellular carcinoma (HCC)." (PMID 37546394, 2023). "Because FOXC1 is an EMT-related gene, and the relationship between FOXC1 and VEGF-A has also been proved in hepatocellular cancer, here, we also revealed that the knockdown of FOXC1/FOXCUT gene pair could lead to VEGF-A down-regulation." (PMID 24889262, 2014).
esophageal cancer (1 paper, 2017). A primary or metastatic malignant neoplasm involving the esophagus. "FOXCUT plays a functional role in the development of esophageal cancer and predicts the survival potentially and partially by modulating FOXC1." (PMID 28388588, 2017). "FOXCUT level was positively correlated with FOXC1 level in esophageal cancer, and the decreased expression of FOXC1 was also observed after being treated by FOXCUT siRNA." (PMID 28388588, 2017). "FOXCUT and FOXC1 levels were both up-regulated in esophageal cancer and strongly correlated with poor differentiation and metastasis." (PMID 28388588, 2017). "In vitro experiments showed that either FOXCUT or FOXC1 silencing could greatly inhibit cell proliferation, colony formation, migration and invasion in esophageal cancer cells." (PMID 28388588, 2017).
lymph node metastasis (1 paper, 2021). "It was demonstrated that the regulation of FOXCUT expression levels was associated with poor differentiation, lymph node metastasis, and a worse prognosis." (PMID 35178357, 2021).
meningioma (1 paper, 2022). A generally slow growing tumor attached to the dura mater. "All clusters and 12/12 meningioma-dura pairs exhibited hypomethylation of the gene promoters of a module associated with the craniofacial patterning transcription factor FOXC1 and its upstream lncRNA FOXCUT." (PMID 35769412, 2022).
prostate carcinoma (1 paper, 2021). A carcinoma that arises from epithelial cells of the prostate gland. "In this study, the transcriptional expression levels of three lncRNAs namely colon cancer associated transcript 2 (CCAT2), HULC, and FOXCUT, and the effect of NaBu on cell cycle control, apoptosis, and expressions of these lncRNAs were evaluated in two prostate cancer cell lines, PC-3 and LNCAP." (PMID 35178357, 2021). "In this study, we investigated the effect of NaBu on the expressions of FOXCUT, HULC, and CCAT2 lncRNAs in two prostate cancers; PC-3 and LNCAP cell lines." (PMID 35178357, 2021).
tumor (5 papers, 2014 to 2025). "LINC01133, like other lncRNAs of interest, such as HOTAIR, MALAT1, TUG1, and FOXCUT, should be at the forefront of clinical research, considering its importance both in the intratumoral context and in the tumor microenvironment." (PMID 40863724, 2025). "Additionally, the results also confirmed that the expression level of angiogenesis factor VEGF-A was reduced after FOXC1 and FOXCUT knockdown, which may indicate a possible role for FOXC1 and FOXCUT in tumor angiogenesis." (PMID 24889262, 2014). "This may suggest a possible role for the FOXC1/FOXCUT gene pair in tumor angiogenesis in OSCC." (PMID 24889262, 2014). "In particular, all tumor subtypes exhibited hypomethylation affecting the promoter of the transcription factor FOXC1 and its upstream lncRNA transcript FOXCUT." (PMID 35769412, 2022). "Recently, the "lncRNA-mRNA pair" formed by lncRNA FOXCUT and mRNA FOXC1, has been verified to play a significant role in tumor progression." (PMID 29416703, 2018). "Knockdown of CCAT2, FOXCUT, HOTAIR, TUG1 and UCA1 can suppress various aspects of tumor progression." (PMID 29416703, 2018). "After FOXCUT and FOXC1 (an EMT-related gene) silencing, the expression levels of MMP2, MMP7, MMP9, and VEGF-A were downregulated, suggesting a possible role for the FOXC1/FOXCUT gene pair in tumor angiogenesis in OSCC." (PMID 41020820, 2025). "In conclusion, FOXC1 may be co-amplified with FOXCUT in OSCC, and both of them may be functionally involved in the tumor progression of OSCC." (PMID 24889262, 2014). "In addition 21 of the 23 patients (91.3 %, p < 0.05) showed remarkably higher expression of FOXCUT lncRNA in tumor tissues than in noncancerous tissues." (PMID 24889262, 2014).
cancer (4 papers, 2014 to 2023). A tumor composed of atypical neoplastic, often pleomorphic cells that invade other tissues. "It exhibits up-regulated expressions of the cancer-associated lncRNAs FOXCUT, SAMMSON, ENSG00000251320, and ENSG00000248927, as well as ion channels in nerve fibers, such as GRIA2 and GABARR1." (PMID 37445678, 2023). "In particular, the cancer-related lncRNA, such as SAMMSON and FOXCUT, belong to the gene network with the cancer-related transcription factor FOXC1." (PMID 37445678, 2023). "In this study, we first identified a new lncRNA-mRNA pair, FOXC1 and its adjacent lncRNA FOXCUT, as the new form of cancer driver gene compound in OSCC." (PMID 24889262, 2014). "Overexpression of this gene promoted cell proliferation, invasion, and migration as well as epithelial-mesenchymal transition (EMT), inhibited cancer cell apoptosis, and blocked the S-phase cell cycle, whereas silencing of lncRNA FOXCUT had the opposite effect." (PMID 35685427, 2022). "FOXCUT and FOXC1 could be represent the potential diagnostic markers and therapeutic targets in the cancer clinic." (PMID 24889262, 2014).
FOXCUT also shares sentences with these, for which no sentence is quoted: colorectal cancer (1 paper); esophageal squamous cell carcinoma (1); gastric adenocarcinoma (1); nasopharyngeal carcinoma (1).